BAD (BCL2 associated agonist of cell death)
Diseases named in the same sentence as BAD in open-access papers (continued):
Sharing a sentence is not in itself a finding about the gene and the disease.
prostate carcinoma (31 papers, 2009 to 2026). A carcinoma that arises from epithelial cells of the prostate gland. "Clinically, high BAD expression was associated with a shorter time to biochemical recurrence in 158 mostly high-risk prostate cancer patients." (PMID 39217197, 2024). "We also identified several downstream targets affected by OTS167 in prostate cancer cells, including the pro‐apoptotic protein BAD and the microtubule‐associated protein stathmin." (PMID 29437778, 2018). "Here we report that a combination of MCL-1 loss and BAD dephosphorylation is sufficient to induce rapid apoptosis in PTEN-deficient advanced prostate cancer cells." (PMID 24040284, 2013). "We also showed that BAD knockdown makes PTEN-deficient prostate cancer LNCaP cells insensitive to apoptosis induced by PI3K inhibitors." (PMID 24040284, 2013). "AZA1 treatment also down-regulated PAK and AKT activity in prostate cancer cells, associated with induction of the pro-apoptotic function of BAD by suppression of serine-112 phosphorylation." (PMID 24040362, 2013). "In addition to this, our results showed a markedly increased expression of BAD in advanced prostate cancer samples, further supporting this genetic identification of the association of BAD with aggressive prostate cancer." (PMID 28674394, 2017). "There are limited studies to link the association between BAD gene and aggressive prostate cancer." (PMID 28674394, 2017). "For example, an earlier study from our group demonstrated that the tumor center of prostate cancer specimens is characterized by a high expression of phosphorylated BAD, a member of the BCL2 family of proteins that regulate apoptosis." (PMID 41545625, 2026). "Knockdown of BAD in prostate cancer cells in vitro led to decreased cell viability and colony growth." (PMID 39217197, 2024). "Numerous protein kinases including AKT1, MAPK1/ERK, RPS6KA1/RSK1, cAMP-activated protein kinase (PKA), PAK1, PRKCI/nPKC-iota, PRKCE/nPKC-epsilon and PIM1 were reported to phosphorylate BAD in prostate cancer cells." (PMID 33668112, 2021). "Increased expression of BAD was reported in prostate carcinoma and correlated with a longer time to biochemical relapse and overall survival." (PMID 33668112, 2021). "Fourth, in a broader context, the effects of propranolol on apoptosis in prostate cancer cells will also depend on other BCL family proteins beside BAD and MCL-1." (PMID 30871232, 2019). "Increased MCL-1 expression and BAD phosphorylation were identified as target molecules responsible for apoptosis inhibition in prostate cancer cells by ADRB2/PKA pathway, whereas the effectors responsible for accelerated migration await further investigation." (PMID 30871232, 2019). "Sensitivity to apoptosis induced by BAD dephosphorylation and loss of MCL-1 expression varies among prostate cancer cell lines as does the expression of anti- and pro-apoptotic BCL proteins." (PMID 30871232, 2019). "This analysis revealed a marginal association between the RTK/ERK pathway genes including BAD (P = 0.058), PDGF-D (P = 0.051) and CCND2 (P = 0.052) and aggressive prostate cancer." (PMID 28674394, 2017). "We identified three genes BAD, CCND2, and PDGF-D with a marginal association with aggressive prostate cancer." (PMID 28674394, 2017). "Contradictive reports appeared that increased BAD expression stimulates proliferation of prostate cancer cells." (PMID 23725574, 2013). "Our data demonstrate that BAD dephosphorylation in itself is insufficient to induce rapid apoptosis in prostate cancer cells." (PMID 24040284, 2013). "Activation of Akt produces a variety of cellular effects, including inactivation of the pro-apoptotic protein BAD and an increased growth of prostate cancer cells in a xenograft model." (PMID 23755281, 2013). "In this study, we used experimental data on the signaling pathways that control BAD phosphorylation to build a dynamic network model of apoptosis regulation in prostate cancer cells." (PMID 24339759, 2013).
prostate carcinoma (continued). "To address this issue, we investigated BAD phosphorylation in Ser112 following AZA1 treatment, since it has been reported that regulation of prostate cancer cell survival involves BAD phosphorylation." (PMID 24040362, 2013). "It has been suggested that n-3 PUFA induces cell apoptosis in prostate cancer via a mechanism of LOX15-mediated SDC-1-dependent suppression of PDPK1/AKT/BAD phosphorylation." (PMID 23762859, 2013). "Previously, we demonstrated that increased BAD expression promotes prostate cancer cell proliferation." (PMID 24040284, 2013). "In contrast, treatments that induce simultaneous BAD dephosphorylation and MCL-1 loss trigger rapid apoptosis in prostate cancer cells." (PMID 24040284, 2013). "These earlier results suggested that PI3K inhibition and subsequent BAD dephosphorylation would trigger apoptosis in PTEN-negative prostate cancer cells." (PMID 24040284, 2013). "Earlier, we demonstrated that treatment with a PI3K inhibitor triggers BAD dephosphorylation at S112 and S136; we also used shRNA knockdown to demonstrate that BAD is necessary for apoptosis induction by PI3K inhibitors in prostate cancer cells." (PMID 24040284, 2013). "Our earlier work described a signaling network of convergent signaling pathways that control BAD phosphorylation and thus, apoptosis in prostate cancer cells." (PMID 24040284, 2013). "Sustained inhibition of Akt-BAD phosphorylation has been reported in prostate cancer cells by quercetin and apigenin." (PMID 23285096, 2012). "Combination of proliferative and apoptotic properties prompts prostate cancer cells to be “addicted” to increased levels of phosphorylated BAD." (PMID 19593445, 2009). "Experiments in tissue culture have shown that expression of BAD stimulates division of prostate cancer cells as well as other cancer cells." (PMID 19593445, 2009). "Analysis of the effect of BAD on prostate cancer xenografts has shown that increased BAD expression enhances tumor growth, while knockdown of BAD expression by shRNA inhibits tumor growth." (PMID 19593445, 2009). "Here we report that increased BAD expression stimulates proliferation of prostate cancer cells in tissue culture and prostate tumor growth in vivo." (PMID 19593445, 2009). "BAD, a pro-apoptotic protein of the Bcl-2 family, has recently been identified as an integrator of several anti-apoptotic signaling pathways in prostate cancer cells." (PMID 19593445, 2009). "A recent study has shown that BAD expression is elevated in prostatic carcinomas compared to low expression in normal prostatic epithelium." (PMID 19593445, 2009). "This combination of proliferative and apoptotic properties creates conditions for prostate cancer cells “addiction” to increased levels of phosphorylated BAD." (PMID 19593445, 2009). "Tissue culture experiments demonstrated that increased BAD expression stimulates proliferation of prostate cancer cells." (PMID 19593445, 2009). "To address the possible role of increased BAD expression, we examined proliferation of prostate cancer cells that overexpress BAD." (PMID 19593445, 2009). "At the same time, BAD dephosphorylation increases sensitivity of prostate cancer cells to apoptosis." (PMID 19593445, 2009). "Collectively, our results suggest that the tumor center is a topological niche with high BAD expression that may drive prostate cancer progression." (PMID 39217197, 2024). "AKT is an important target in prostate cancer therapy and modulates BAD, c-JUN and ERK." (PMID 32414345, 2020). "Likewise CK2α, PIM1 is overexpressed in prostate cancer, leukemia and lymphomas and promotes oncogenesis by phosphorylation of BAD and collaboration with MYC23." (PMID 29042609, 2017).
prostate carcinoma (continued). "Similarly, it is found that BAD is a pro-apoptotic protein which has been identified as an integrator of several anti-apoptotic signaling pathways in prostate cancer cells." (PMID 27993151, 2016). "BAD is a convergence point for several anti-apoptotic signaling pathways in prostate cancer cells." (PMID 24339759, 2013). "The results presented in this paper show that BAD, the BH-3 only Bcl-2 protein, might function in a dual capacity in prostate cancer." (PMID 19593445, 2009). "Also, we have recently shown that in prostate cancer cells, the pro-apoptotic Bcl-2 protein BAD plays a unique role as a convergence point of several anti-apoptotic signaling pathways that include constitutively active PI3K, activated EGFR and GPCR." (PMID 19593445, 2009). "Reports on increased expression of BAD in prostate cancer led us to suggest that prostate cancer cells may benefit from maintaining BAD expression." (PMID 19593445, 2009). "Increased levels of BAD in prostate carcinomas have also been reported." (PMID 19593445, 2009). "Similarly, ectopic BAD expression increased prostate cancer cell number and tumor growth." (PMID 31942016, 2020). "AKT is activated in 50% of breast and prostate cancers and promotes tumorigenesis by teaming with 14-3-3 to regulate key proteins involved in cellular transformation, such as FoxO transcription factors, the pro-apoptotic protein BAD and the cell cycle regulator p27Kip1 among others." (PMID 25740432, 2015). "In prostate cancer cell lines, the proteins of BCL-2 family MCL1, BAK, BAD and BIM can be regulated by signal transduction pathways amenable for pharmacological targeting." (PMID 33668112, 2021). "In prostate cancer cells, the activation of RAS/ERK signaling inhibited apoptosis by phosphorylating BAD and by suppressing BIM expression." (PMID 33668112, 2021). "It has been shown that ADRB2/PKA signaling can phosphorylate BAD and dissociate it from BCL-XL and also upregulate MCL-1 levels in prostate cancer cells." (PMID 30871232, 2019). "This genetic study implicates the association of the SNPs rs3217869 (CCND2) and rs12643184 (PDGF-C), and the genes BAD, PDGF-D and CCND2 in the RTK/ERK signaling pathway with aggressive prostate cancer." (PMID 28674394, 2017). "In summary, our combined SNP- and gene-based analyses revealed the association of two novel loci (rs3217869/CCND2 and rs12643184/PDGF-C), and three genes (BAD, PDGF-D and CCND2) in the RTK/ERK signaling pathway with aggressive prostate cancer." (PMID 28674394, 2017). "In future work, we will integrate elements downstream of BAD, such as BclXL, BAX and BAK, to investigate a more detailed mechanism related to stress interactions in prostate cancer." (PMID 24339759, 2013). "In the present study, our results demonstrate that green tea polyphenols induce apoptosis in prostate cancer cells by activating the FAS death receptor/caspase-8 pathway and inhibiting the p-Akt/p-BAD cell survival pathway." (PMID 23285096, 2012). "Hesperetin also promotes apoptosis in prostate cancer cells by activating BAX and BAD expression." (PMID 38200039, 2024). "However, we found that despite rapid BAD dephosphorylation, PI3K inhibition with ZSTK474 induces apoptosis in C42Luc prostate cancer cells at relatively late time points (between 12–24 hours)." (PMID 24040284, 2013). "Earlier publications from several laboratories, including ours, showed that phosphorylation of the BH3-only protein BAD plays a central role in apoptosis regulation downstream of the PI3K signaling pathway in various cell lines, including the prostate cancer cell lines LNCaP and C42." (PMID 24040284, 2013). "Collectively, the mechanism of BAD inactivation by dysregulated PI3K/Akt signaling may be an important resistance mechanism in both PTEN‐deleted and PTEN–wild‐type prostate cancer and highlights a novel therapeutic strategy to increase apoptotic response to AR antagonists." (PMID 31228231, 2019).
prostate carcinoma (continued). "The BAD protein represents a switch integrating the antiapoptotic effects of multiple pathways in prostate cancer cells, thus expression of a nonphosphorylatable mutant S112A-BAD reduces the survival effects of growth factors such as EGF in prostate cancer cells." (PMID 24040362, 2013). "The expression of both pro-apoptotic (BAX,BIK, and BAD) and anti-apoptotic genes(MCL-1 and BCL-XL) was not affected byBAP1-knockdown in prostate cancer cells." (PMID 32422649, 2020).
lung carcinoma (15 papers, 2011 to 2025). "Therefore, we attempted to elucidate the mechanism by which circSORBS1 inhibits lung cancer development by regulating the RUFY3/YHWAE/BAD/BCL2 pathway through rescue experiments." (PMID 38915053, 2024). "The observation of BAD S111 phosphorylation in a lung cancer cell line and several MPNST cell lines suggests that S111 phosphorylation could be used as pharmacodynamic marker of Pak activity in some cancers." (PMID 22096607, 2011). "By exploring the underlying mechanism, we found that circSORBS1 regulates RUFY3 expression directly and indirectly, activates the YWHAE/BAD/BCL2 apoptosis signalling pathway, and ultimately inhibits the development of lung cancer." (PMID 38915053, 2024). "In summary, we elucidated that circSORBS1 activates the RUFY3/YWHAE/BAD/BCL2 signalling pathway through both a sponging mechanism and direct mRNA binding, ultimately inhibiting the development of lung cancer." (PMID 38915053, 2024). "This dual regulatory mechanism leads to an increase in RUFY3 protein levels, which ultimately activates the YWHAE/BAD/BCL2 apoptotic signalling pathway and suppresses lung cancer progression." (PMID 38915053, 2024). "We further determined the protein levels of PUMA and BAD proteins in both untreated and caffeine/cisplatin-treated HTB182 and CRL5985 lung cancer cells." (PMID 25937999, 2015). "To address if S111 of BAD is phosphorylated in other cell lines besides 293T cells, we probed a panel of malignant peripheral nerve sheath tumor (MPNST) cells and one lung cancer cell line (H358)." (PMID 22096607, 2011). "Additionally, it has been reported that the PI3K/AKT pathway is involved in blocking apoptosis in lung cancer cell lines; p-AKT increases radioresistance by inhibiting the pro-apoptotic proteins BAD, BAX, and caspase-9." (PMID 34760374, 2021). "In both human and mouse lung cancer cell lines, knocking down HSP90AA1 promoted cell apoptosis through the inhibition of the pro-survival effect of AKT1 by decreasing the phosphorylation of itself and its downstream factors of mTOR and BAD, as well as downregulating Mcl1, Bcl-xl, and Survivin." (PMID 35095481, 2021). "Interestingly, in our lung carcinoma model, we have shown that BAD is phosphorylated at Ser-112 and not at Ser-136, thereby confirming our findings that TIMP-1 activated cell survival does not involve Akt activation." (PMID 26366732, 2015). "While the mTOR and MAPK cascade interactions are known to play a relevant role in lung cancer cell signal transductions, to our knowledge the interaction between p90RSK and BAD in the anti-apoptotic process has never been described and might represent a potential prognostic factor in lung cancer." (PMID 29137348, 2017).
melanoma (15 papers, 2013 to 2025). A malignant, usually aggressive tumor composed of atypical, neoplastic melanocytes. "Interestingly, the knockdown of CRAF in melanoma cells with non V600E mutations in BRAF induced apoptosis through a reduction in BAD phosphorylation and Bcl-2 expression." (PMID 25422890, 2014). "The overexpression of BRAF decreases anoikis induced cell death in melanoma cells through increased phosphorylation of BAD S75." (PMID 38434478, 2024). "In melanoma, BAD is phosphorylated through MEK/ERK dependent signalling, supporting cell survival, this is an adaptation from melanocytes where these phosphorylation’s are mainly driven by the RSK signalling pathway." (PMID 38434478, 2024). "Taken together, these results identify PAK inhibitors as agents that can block the progression of early stage, BRAF mutant, RhoJ expressing melanomas by modulating BAD signaling." (PMID 28753606, 2017). "Previous studies have demonstrated that the BRAF oncogene protects melanoma cells from anoikis by modulating BAD signaling." (PMID 28753606, 2017). "Short-term treatment of nascent melanoma tumors with PAK inhibitors that block RhoJ signaling halts the growth of BRAF mutant melanoma tumors in vivo and induces apoptosis in melanoma cells in vitro via a BAD-dependent mechanism." (PMID 28753606, 2017). "Based on CD133’s activation of an AKT/p-BAD survival pathway in trametinib-treated human melanoma stem cells as a mechanism for trametinib resistance, we next targeted the AKT pathway in BAKP and POT cells harboring NRASQ61K and NRASQ61R mutations, respectively." (PMID 39996721, 2025). "In vivo the increased survival of CD146-transduced melanoma cells was demonstrated by the cellular inhibition of the pro-apoptotic protein BAD, the cellular resistance to staurosporine-induced cell death, and the cleavage of caspase 3, an early event during apoptosis." (PMID 25685061, 2015). "Knockdown of BAD also led to marked inhibition of proliferation in A375 and SK-MEL-28 malignant melanoma cells, and this growth inhibition could be abrogated by overexpression of wild type BAD." (PMID 23725574, 2013). "Collectively, these studies indicated that the increase in in vivo tumourigenesis by the enforced expression of huCD146 in melanoma cells enhanced the survival of the cells by promoting phospho-AKT and inactivating BAD in the tumours." (PMID 25685061, 2015). "We also found that the identified BAD and CHCHD2 mutations frequently occur in melanoma but not in other cancers via The Cancer Genome Atlas analysis." (PMID 34900699, 2021). "While FRAX597 does have some effects on modulating MAP kinase signaling, these agents do not synergize with Vemurafenib to kill melanoma cells suggesting that these agents induce apoptosis by modulating BAD and not by modulating MAPK signaling." (PMID 28753606, 2017). "BCL10 (3.84-fold), TRADD (2.71-fold), CYCS (2.51-fold), DIABLO (2.43-fold), BAD (2.36-fold), BID (2.17-fold), TNFSF8 (2.13-fold), TNFSF10 (2.11-fold), BAX (2.03-fold), and FAS (2.01-fold) were also proapoptotic genes highly upregulated in response to UA treatment in A-375 melanoma cells." (PMID 39473730, 2024).